IL10 (interleukin 10)
Diseases named in the same sentence as IL10 in open-access papers (continued):
Sharing a sentence is not in itself a finding about the gene and the disease.
malaria (continued). "This study aims to evaluate the CD4+ and CD8+ T cells, leucocytes subpopulations, IL-6, IL-10 and biomarkers of oxidative stress among children infected with varying grades of malaria attending the University of Abuja Teaching Hospital and National Hospital, Abuja, Nigeria." (PMID 35223394, 2021). "However, to date, no studies have investigated the impact of Tr1 cells on Tfh cell development during malaria in humans, despite an important agonistic role of IFNγ and IL-10 on Tfh during murine Plasmodium infection." (PMID 36845571, 2021). "That IL-10 was detectable in the plasma of asymptomatically infected adults and at high levels in children with acute malaria is consistent with an important role for this regulatory cytokine in malaria." (PMID 33407502, 2021). "Additionally, we found that even in the uninfected control group, history of previous malaria episodes was associated with reduced perturbation of indirect bilirubin, total bilirubin, CCL2, CXCL10, IL-10 and IFN-γ." (PMID 34727121, 2021). "When stratifying by P falciparum infection, elevated BAFF and downregulated CCL2 and IL‐10 were independently associated with nodding syndrome in children who were malaria‐positive and malaria‐negative." (PMID 34033255, 2021). "Pro/anti-inflammatory (IL-6/IL-10) ratio was higher in clinical than asymptomatic malaria." (PMID 33253198, 2020). "In vivo, the reduced CD4+ T cell IL-10 expression in Malat1−/−mice underpins enhanced immunity and pathogen clearance in experimental visceral leishmaniasis (Leishmania donovani) but more severe disease in a model of malaria (Plasmodium chabaudi chabaudi AS)." (PMID 32321759, 2020). "The long-term protection of ITV was shown to be related to the increase in the number of CD19+CD1dhiCD5hi B (B10) cells, which may negatively regulate the long-term protective effect of malaria ITV by secreting IL-10." (PMID 32257991, 2020). "Also, it has been shown that the levels of TNF-α, IL-2, IL-10, IL-6 in Plasmodium-helminth co-infected individuals were significantly higher than the malaria-positive (MP) group dampening the immune response to malaria." (PMID 33170876, 2020). "In our study, CD4hiCD38hi cells were increased in proportion to malaria disease severity, and there are phenotypic analogies between the CD4hiCD38hi T cells identified herein and IL‐10‐expressing CD4+ T cells that were shown to limit immunopathology in a rodent malaria model." (PMID 33282291, 2020). "One hypothesis, therefore, is that malaria‐induced neutrophil dysfunction results from hemolysis‐ and IL‐10‐driven HO‐1 induction." (PMID 30570786, 2019). "In experimental malaria caused by P. yoelli infection of C57BL/6 mice, B cell intrinsic IL-10 signaling enhanced germinal center (GC) B cell responses by limiting IFNγ activity and subsequent Tbet expression by these cells, thereby promoting antibody production and parasite clearance." (PMID 30809232, 2019). "Given that these γδ T cells produce IL-10 and can provide help to B cells for antibody production, they may play a role in the acquisition of natural immunity against malaria." (PMID 30809232, 2019). "Therefore, given these beneficial and detrimental roles for IL-10 during malaria, it is critically important that we improve our understanding about how IL-10 production is regulated and the specific roles for IL-10 produced by different cell populations." (PMID 30809232, 2019). "In addition, increased levels of IL-6 and IL-10, and decreased levels of RANTES were detected in 2010; these three cytokines have been associated with severe malaria." (PMID 31806027, 2019). "The immunomodulatory function of IL-10 and TGF-β is associated with Tregs whose role in rodent malaria remains unclear." (PMID 30774635, 2019). "Therefore, data from mouse models of malaria indicates that IL-10 is required to protect host tissue from inflammation, but by doing so, can also promote growth of parasites and associated disease manifestations." (PMID 30809232, 2019).
malaria (continued). "The ratio of plasma IL-10 to TNF plays an important role in determining whether children with malaria develop anemia." (PMID 30809232, 2019). "However, compared with the other groups, anti-inflammatory cytokines including IL-10 and IL-4, were lower in women with Malaria+CHB." (PMID 31002731, 2019). "IL-10 production by Th1 cells has emerged as an important mechanism to dampen inflammation in the face of intractable infection, including in African children with malaria." (PMID 30809232, 2019). "Further, elevated levels of IL-10 in uncomplicated malaria with a high peak during SM were seen." (PMID 31614626, 2019). "The balance between pro- and anti-inflammatory responses in malaria progression could be best characterized by the expression levels of IL-12 and IL-10 in malaria clinical forms and are equivocally debated too." (PMID 31614626, 2019). "Therefore, key transcriptional regulators of IL-10 production have been identified with potentially important roles in malaria, although many still need to be validated with samples from pre-clinical models of malaria or malaria patients." (PMID 30809232, 2019). "We found that all Bubi individuals possessed the malaria-resistant allele of the ACKR1 and CD36 genes, in addition to certain variations in other genes such as G6PD, ATP2B4, GRK5, and IL-10." (PMID 30841922, 2019). "Data from mouse models of malaria indicates that IL-10 is required to protect host tissue from inflammation, but may also promote growth of parasites and associated disease manifestations." (PMID 31604978, 2019). "Similarly, TGFβ was reported to play a protective role against severe malaria in mice, and TGFβ can drive IL-10 production by several different CD4+ T cell subsets, including Treg, Th17 and other FoxP3-negative cells." (PMID 30809232, 2019). "However, only the IL-10 cytokine levels were affected in cases of malaria and intestinal parasite co-infection." (PMID 29293589, 2018). "The effect of ITN use on malaria incidence in mothers may influence IL-10 production in fetal cells, and this phenomenon may be modulated by parity-acquired immunity." (PMID 29743113, 2018). "On the basis of these findings, this study was designed to further characterize the effect of prenatal exposure to P. falciparum antigens on cytokine response during clinical malaria episodes focusing on IL-10 and IFN-γ, which are anti-inflammatory and pro-inflammatory cytokines, respectively." (PMID 30154871, 2018). "Given that optimal induction of proinflammatory cytokines (e.g., IFN-γ and TNF-α), and the counterbalance exerted by anti-inflammatory cytokines (TGF-β and IL-10) are crucial for determining the outcome of blood-stage malaria, we first analyzed the serum levels of these molecules." (PMID 30462731, 2018). "Moreover, high levels of IL-10 were detected in the culture supernatants of PBMCs from the malaria-endemic groups." (PMID 28769886, 2017). "Together, these data suggest that a final switch from IFNγ to IL10 production among malaria-specific CD4+ T cells may play a role for in mediating tolerance to malaria." (PMID 29097996, 2017). "These clinical observations are consistent with the finding that young children mounted an exuberant anti-inflammatory IL10 response, which might limit the inflammatory pathology observed in adults during a first episode of malaria." (PMID 29284469, 2017). "However, IL-10, which is considered a critical anti-inflammatory mediator in regulating the pro-inflammatory response during malaria, showed significant correlation with parasite density in children residing in Accra and Kintampo." (PMID 28399920, 2017). "However, studies involving another group of patients suffering P. vivax malaria found high levels of IFN-γ and IL-10 in patients with previous episodes of malaria." (PMID 28243235, 2017).
malaria (continued). "In the few published studies which have used multicolor flow cytometry to assess Pf-specific cytokine production by CD4 T cells at an individual cell level, it has been shown that the Pf-specific CD4 T-cell response in highly malaria-exposed children is dominated by IFNγ and IL10 coproducing cells." (PMID 29097996, 2017). "In addition, the results indicated that IL-10 plasma levels are influenced by parasitaemia and number of previous malaria episodes." (PMID 28118834, 2017). "Regarding the association between IL-10 plasma levels with parasitaemia and number of previous malaria episodes, in the present study, it was observed higher IL-10 plasma levels in patients with high parasitaemia (>501 parasites/cu mm) and with more than five previous malaria episodes." (PMID 28118834, 2017). "Importantly, we also noticed a trend towards a decreased IL10+ to IFNγ+ T cell ratio in our patients with severe cerebral malaria compared to patients with uncomplicated malaria but our sample size of patients with severe cerebral malaria was low (n = 3)." (PMID 27802341, 2016). "Thus, Blimp-1 expression in T cells enhanced parasite growth and was critical for the generation of IL-10-producing Tr1 cells during experimental malaria." (PMID 26765224, 2016). "Moreover, IL-10 contributes to the protection against experimental cerebral malaria observed in mice with helminth or heterologous malaria parasite coinfections, as well as that induced in mice following repeated rounds of infection and drug cure (9, –, 11)." (PMID 26459508, 2016). "Moreover, the recurrent malaria group displayed significantly augmented levels of IL-10, IL-6, and IL-4 as compared to patients with primary malaria (p < 0.0005, p < 0.005 and p < 0.05, respectively)." (PMID 27581163, 2016). "Thus, the role of IL-10 in malaria, and possibly in babesiosis, remains controversial because high concentrations have been shown to be associated with both severe disease and protection against P. falciparum infections." (PMID 26953797, 2016). "The blockade showed a stronger effect on cytokine production and increased the malaria-specific IFNγ and IL10 production of all patients who exhibited a cytokine response to P. falciparum and demarcated a positive IFNγ response in one patient who was priorly unresponsive." (PMID 27802341, 2016). "Hence, it is reasonable to think that the malaria outcome depends on the ability of parasite to regulate the inflammatory response by induction of IL-10 production." (PMID 26943639, 2016). "The hypothesis that IL-10 would have a protective role against complications of recurrent malaria still requires further investigation." (PMID 27581163, 2016). "Our data also support that blockade of IFNAR signaling or neutralization of Tr1 effector molecules IFN-γ and IL-10 during malaria may bolster Plasmodium-specific Tfh responses, enhance parasite control, and promote the establishment of humoral immunity." (PMID 27732671, 2016). "IL-10 levels were markedly (300 to 5,000 fold) elevated in those with malaria." (PMID 27385484, 2016). "In this study, the P. chabaudi murine model of malaria in IL-10−/− mice was used." (PMID 27557867, 2016). "In this study, levels of the IL-10, IL-6 and IL-4 were higher in patients with recurrent malaria." (PMID 27581163, 2016). "Importantly, IFNγ+IL10+ Th1 cells have been shown recently to prevent immunopathology in rodent models of toxoplasmosis and malaria." (PMID 27802341, 2016). "Two studies in Pará state, Brazil, also described no haplotype associations of the IL10 gene with malaria and falciparum malaria in Africa." (PMID 27999453, 2016). "We tested relationships between plasma arginase activity, plasma sCD163, and plasma IL-10 with selected parameters of malaria disease activity and NO-related measures—HRP-2, angiopoietin-2, plasma lactate, plasma arginine, the arginine/ADMA ratio, blood hemoglobin, and blood platelets." (PMID 27385484, 2016).
malaria (continued). "Interestingly, it was verified that the IL-10 levels in patients with recurrent malaria were directly proportional to the number of malaria episodes." (PMID 27581163, 2016). "Notably, a recent study identified that frequencies of IFN-γ and IL-10 co-producing CD4 T cells were increased in Ugandan children who presented with >2 malaria episodes/year, compared to children who presented with <2 malaria episodes/year." (PMID 27732671, 2016). "IL-10 is a key immunomodulatory cytokine and plays an important role in mouse models of malaria." (PMID 27660116, 2016). "This concept is further supported by the observation by us and others that IFNγ to IL10 ratios might be altered in patients with severe malaria." (PMID 27802341, 2016). "Our previous studies using a lethal model of malaria demonstrated that IFNAR1- signalling occurred via cDC, which resulted in potent suppression of Th1-immunity, and was associated with effects on PDL1, PDL2 and IL-10 expression by cDC subsets." (PMID 27812214, 2016). "This hypothesis is reinforced by a murine model where it was demonstrated that IL-10 depleted mice are able to control parasite replication during P. chabaudi AS infection, however, they develop a severe malaria mediated by inflammatory cytokine action." (PMID 26943639, 2016). "Furthermore, we identified that type I IFN-mediated induction of Tr1- associated cytokines IL-10 and IFN-γ collaborate to limit the generation of protective humoral immunity during experimental malaria." (PMID 27732671, 2016). "Both, IFNγ and IL10, play critical roles in the immune homeostasis in acute malaria." (PMID 27802341, 2016). "Of relevance, high ratios of plasma proinflammatory to anti-inflammatory cytokines, including IL-10, are a common feature of severe malaria disease, emphasizing the importance of infection-instructed immune balance in enabling optimal control of malaria infection." (PMID 27630165, 2016). "Thus, the PBMC of malaria patients were stimulated with iRBC and their production of IFNγ, IL10, TNFα, and IL13 was measured by intracellular staining." (PMID 27802341, 2016). "Indeed, we found that the PD1+CTLA4+CD4+ Teff cells in our malaria patients produced the regulatory cytokine IL10 in response to P. falciparum-antigens." (PMID 27802341, 2016). "CD4+cells from individuals with fewer previous episodes of malaria were more inflammatoryand had greater TNF production, whereas responses from CD4+ T-cells fromsubjects with more frequent previous episodes of malaria were more typical of regulatoryT-cells in that they produced IL-10." (PMID 26676319, 2015). "Subjects with mild malaria exhibited the highest plasma levels of IL-10." (PMID 26466783, 2015). "Severe malaria was also associated with higher levels of IL-1β (p = 0.008), IL-2 (p = 0.001), IL-4 (p = 0.041), IL-12p70 (p = 0.010), IL-13 (p = 0.004), IFN-γ (p = 0.041), TNF (p = 0.049), IFN-γ/IL-10 (p = 0.016), TNF/IL-10 (p = 0.016) and (TNF + IFN-γ)/IL-10 (p = 0.001) than mild malaria." (PMID 26466783, 2015). "Malaria infected female mice were shown to have higher IL-10 levels compared to males." (PMID 26020962, 2015). "As a consequence, the in vivo efficacy of MSC treatment against malaria was evaluated in a mouse model of P. berghei infection; administration of MSCs was found to confer host resistance against malaria through increasing IL-12 production, and suppressing IL-10 and regulatory T cell production." (PMID 26253514, 2015). "One mechanism of self-regulation by CD4+ Th1 cells in malaria is the induction of IL-10." (PMID 25628621, 2014). "Following malaria there was a marked shift in the response to iRBCs with the same children's immune cells producing lower levels of pro-inflammatory cytokines and higher levels of anti-inflammatory cytokines (IL-10, TGF-β)." (PMID 24743880, 2014).
malaria (continued). "In malaria, induction of the immunoregulatory cytokine interleukin-10 (IL-10) has been shown to prevent excessive and potentially fatal pathology in murine models of cerebral malaria, and this important role of IL-10 has been corroborated by observational data from malaria patients." (PMID 24787713, 2014). "In conclusion, our results provide evidence that malaria parasite-induced IL-10, a response that limits pathology in the context of malaria, compromises innate immune responses to S. Typhimurium, a prevalent invasive bacterial infection, by compromising the function of phagocytic cells." (PMID 24787713, 2014). "Despite evidence that IL-10 plays a critical role in regulating Plasmodium-induced inflammation in murine models, the cellular sources of IL-10 and the functionality and kinetics of IL-10-producing cells in the context of human malaria remain unclear." (PMID 24743880, 2014). "Low levels of IL-10 and TGF-ß have been associated with severe malaria." (PMID 24934404, 2014). "Significantly, the prevalence of IL-10-producing Th1 cells in Gambian children with asymptomatic malaria was greater than in children with severe disease, indicating that these cells may protect against damaging inflammation during acute malaria." (PMID 25352846, 2014). "Our study highlights the role of IL-10 and hepcidin during blood stage malaria and at least in part demonstrates how hepcidin secretion may be stimulated by raised IL-10 during malarial infection." (PMID 24520384, 2014). "Although previous data have reported monocytes as the main source of IL-10 among cells from the innate immune system during malaria, this immunomodulatory cytokine can also be produced by T cells subpopulation such as T regulatory cells (Treg) in P. falciparum infection." (PMID 24741587, 2014). "Previous studies have implicated heme, released via lysis of infected erythrocytes, or hemozoin, the product of hemoglobin degradation by malaria parasites, in induction of IL-10 expression by macrophages, but the mechanism by which this occurs is unknown." (PMID 24787713, 2014). "We further observed that heavy malaria exposure was associated with a decreased ability of CD4+ T cells to proliferate in response to malaria antigens, and that this impaired proliferation is partially reversed by IL-10 blockade." (PMID 24415936, 2014). "More recently, Gitau and colleagues described malaria-specific co-production of IFNγ and IL-10 following stimulation of CD4+ T cells with a variety of expressed PfEMP variants, although these co-producing cells represented a minor fraction of the total antigen-specific CD4+ T cell response." (PMID 24415936, 2014). "IL-10 can also be induced in IL-17-producing CD4+ T-cells, as yet by unknown pathways, and thus, IL-10 may be a more general mechanism for regulating any subset of CD4+ T-cells in malaria." (PMID 25628621, 2014). "The importance of IL-27 for the generation of IL-10-producing Th1 cells has now been reported in mouse models of malaria, leishamaniasis, and toxoplasma, although, surprisingly, the generation of these cells was independent of IL-21 in mice infected with P. chabaudi." (PMID 25352846, 2014). "Malaria patients in their turn, display a strong correlation between the levels of IL-6 and IL-10." (PMID 24741587, 2014). "Meanwhile, high levels of the anti-inflammatory cytokine IL-10, or high IL-10/TNF-α ratios, reduce the risk of severe malarial anemia, despite being associated with reduced parasite clearance in children with uncomplicated malaria." (PMID 24130857, 2013). "Understanding how these regulatory cells are induced could help to explain differences in IL-10 production in human malaria." (PMID 24041406, 2013). "However, a negative correlation was detected between plasmatic levels of IL-10 and the number of previous malaria infection (p = 0.0186; r = - 0.3958) in malaria individuals." (PMID 24041406, 2013).